FOXC1 (forkhead box C1)
Description:
DNA-binding transcriptional factor that plays a role in a broad range of cellular and developmental processes such as eye, bones, cardiovascular, kidney and skin development. Acts either as a transcriptional activator or repressor. Binds to the consensus binding site 5'- [G/C][A/T]AAA[T/C]AA[A/C]-3' in promoter of target genes. Upon DNA-binding, promotes DNA bending. Acts as a transcriptional coactivator. Stimulates Indian hedgehog (Ihh)-induced target gene expression mediated by the transcription factor GLI2, and hence regulates endochondral ossification (By similarity). Also acts as a transcriptional coregulator by increasing DNA-binding capacity of GLI2 in breast cancer cells. Regulates FOXO1 through binding to a conserved element, 5'-GTAAACAAA-3' in its promoter region, implicating FOXC1 as an important regulator of cell viability and resistance to oxidative stress in the eye. Cooperates with transcription factor FOXC2 in regulating expression of genes that maintain podocyte integrity (By similarity). Promotes cell growth inhibition by stopping the cell cycle in the G1 phase through TGFB1-mediated signals. Involved in epithelial-mesenchymal transition (EMT) induction by increasing cell proliferation, migration and invasion. Involved in chemokine CXCL12-induced endothelial cell migration through the control of CXCR4 expression (By similarity). Plays a role in the gene regulatory network essential for epidermal keratinocyte terminal differentiation. Essential developmental transcriptional factor required for mesoderm-derived tissues, such as the somites, skin, bone and cartilage. Positively regulates CXCL12 and stem cell factor expression in bone marrow mesenchymal progenitor cells, and hence plays a role in the development and maintenance of mesenchymal niches for haematopoietic stem and progenitor cells (HSPC). Plays a role in corneal transparency by preventing both blood vessel and lymphatic vessel growth during embryonic development in a VEGF-dependent manner. Involved in chemokine CXCL12-induced endothelial cell migration through the control of CXCR4 expression (By similarity). May function as a tumor suppressor.
Synonyms: FREAC-3; FKHL7; FREAC3; ARA; IGDA; IHG1; ASGD3; IRID1; RIEG3
Tractability: PROTAC: UniProt records ubiquitination sites on it; ubiquitination databases record sites on it.
Gene: Protein-coding gene on chromosome 6 (1,609,915 to 1,613,897, forward strand). Ensembl gene ENSG00000054598.
Subcellular location: Nucleus
Subcellular location (Human Protein Atlas): Nucleoplasm; Cytosol
Pathways (Reactome):
Developmental Biology: Formation of intermediate mesoderm; Formation of the ureteric bud
Gene Ontology:
Molecular function: DNA binding; DNA binding, bending; DNA-binding transcription activator activity, RNA polymerase II-specific; DNA-binding transcription factor activity; DNA-binding transcription factor binding; protein binding; RNA polymerase II transcription regulatory region sequence-specific DNA binding; RNA polymerase II-specific DNA-binding transcription factor binding; sequence-specific DNA binding; transcription cis-regulatory region binding; DNA-binding transcription factor activity, RNA polymerase II-specific; promoter-specific chromatin binding; RNA polymerase II cis-regulatory region sequence-specific DNA binding
Biological process: cell migration; cell population proliferation; cellular response to epidermal growth factor stimulus; eye development; heart development; negative regulation of mitotic cell cycle; odontogenesis of dentin-containing tooth; positive regulation of DNA binding; positive regulation of DNA-templated transcription; positive regulation of epithelial to mesenchymal transition; positive regulation of keratinocyte differentiation; positive regulation of transcription by RNA polymerase II; regulation of DNA-templated transcription; anatomical structure morphogenesis; cell differentiation; cellular response to chemokine; cerebellum development; chemokine-mediated signaling pathway; endochondral ossification; glomerular epithelium development; kidney development; maintenance of lens transparency; mesenchymal cell development; negative regulation of angiogenesis; negative regulation of lymphangiogenesis; and 10 more
Cellular component: heterochromatin; nucleoplasm; nucleus; chromatin
Genetic constraint (gnomAD): Loss-of-function variants: 5 observed, 8.21 expected, observed/expected ratio (o/e) 0.61, 90% interval 0.32 to 1.28. That is too few expected variants to judge how well the gene tolerates losing a copy. Missense variants: 940 observed, 679.81 expected, observed/expected ratio (o/e) 1.38, 90% interval 1.31 to 1.46. Synonymous variants: 552 observed, 339.61 expected, observed/expected ratio (o/e) 1.63, 90% interval 1.51 to 1.74.
Gene-disease validity (ClinGen):
ClinGen rates the evidence that FOXC1 causes each of these diseases.
FOXC1-related anterior segment dysgenesis (autosomal dominant): Definitive. Any anterior segment dysgenesis in which the cause of the disease is a mutation in the FOXC1 gene.
Homologues: Orthologues: chimpanzee FOXC1 (99% identical), macaque FOXC1 (99% identical), mouse Foxc1 (93% identical), rat Foxc1 (93% identical), pig FOXC1 (91% identical), tropical clawed frog foxc1 (69% identical), zebrafish foxc1a (66% identical). Paralogues in human: FOXC2 (49% identical), FOXS1 (23% identical), FOXE1 (20% identical), FOXL1 (20% identical), FOXA1 (20% identical), FOXD1 (20% identical), FOXD3 (20% identical), FOXA2 (19% identical), FOXD2 (19% identical), FOXE3 (19% identical), FOXL2 (19% identical), FOXJ3 (18% identical), and 29 more.
Diseases named in the same sentence as FOXC1 in open-access papers:
FOXC1 is named in the same sentence as 242 diseases in open-access papers, as found by Europe PMC text mining. Sharing a sentence is not in itself a finding about the gene and the disease. The quoted sentences say what the papers report.
breast carcinoma (119 papers, 2010 to 2026). "Studies have reported upregulated FOXC1 expression in basal-like breast cancer, with high levels of FOXC1 associated with poor prognosis in breast and other cancers." (PMID 41333181, 2025). "Enhanced FOXC1 expression in breast cancer cells is associated with increased acetylation of histone H3, which is regulated by O‐GlcNAc transferase depletion." (PMID 40703976, 2025). "FOXC1 was also associated with poor prognostic subtype of basal‐like breast cancers due to its role in mesodermal tissue development." (PMID 39404228, 2024). "A previous study indicated that FOXC1 can promote the c-Myc expression in breast cancer, indicating the involvement of c-Myc underlying the oncogenic role of FOXC1." (PMID 35096062, 2022). "In lung cancer, FOXC1 expression is higher in tumors compared with normal tissues, and in breast cancer, FOXC1 expression is associated with a poor prognosis." (PMID 35406487, 2022). "Several studies have linked FOXC1 activity to the aggressive phenotype in cancer cells, especially in basal-like breast cancer and hepatocellular carcinoma." (PMID 34948036, 2021). "H3K27me3 is present in lower grade tumors, Luminal A and B1 subtypes where it associates with repression of the Forkhead Box C1 (FOXC1) gene in Luminal B breast cancer, resulting in metastatic behavior." (PMID 33803458, 2021). "FOXC1 is involved in tumor development and metastasis and associated with poor prognosis in basal-like breast cancer." (PMID 32854705, 2020). "Currently, out of all the associations FOXC1 has with different forms of cancer, FOXC1's relationship with breast cancer, specifically BLBC, is the most elucidated." (PMID 29487724, 2018). "Elevated FOXC1 expression is associated with poor prognosis in various cancer types, in particular basal-like breast cancer (BLBC)." (PMID 29560120, 2018). "Elevated FOXC1 mRNA expression is associated with a worse overall survival of breast cancer patients, as well as with brain and lung metastasis of breast cancer." (PMID 30564302, 2018). "Of note, loss of expression of FOXC1 suppresses cancer cell growth and reverts fibroblast-like cells to epithelial-like cells in a mammary carcinoma model." (PMID 30360388, 2018). "FOXC1 expression is significantly associated with expression of MMP7 in breast cancer samples and cell lines at both the mRNA and protein levels." (PMID 29552326, 2018). "In this study, we sought to demonstrate the clinicopathologic significance of FOXC1 expression in BRCA-associated breast cancer." (PMID 27708239, 2016). "Another related transcription factor FOXC1 was associated with the EMT observed in disseminated circulating breast cancer cells and has been linked to the induction of EMT in breast cancer cells." (PMID 23907184, 2013). "Previous studies have demonstrated that these transcription factors play critical roles in various cancers; for example, HINFP shows significant regulatory effects in bladder cancer, POU2F2 is linked to lung cancer, and JUND and FOXC1 are key in colorectal and breast cancer, respectively." (PMID 40417238, 2025). "In breast cancer, FOXC1 expression is also positively associated with brain and lung metastases." (PMID 38183514, 2024). "Furthermore, patients with basal-like breast cancer have a worse forecast, and FOXC1 is positively linked to cancer spread." (PMID 37626655, 2023). "Additionally, the transcription factor forkhead box C1 (FoxC1), which is linked to breast cancer invasiveness, was highly expressed in samples assigned to the hot tumor subgroup." (PMID 36139700, 2022). "Furthermore, in breast cancer patients with ER-positive primary tumors who received tamoxifen treatment, FOXC1 expression is associated with decreased or undetectable ER expression in recurrent tumors post endocrine treatment." (PMID 34540690, 2021). "Interestingly, another study of luminal B breast cancer found that FOXC1 expression was associated with impaired invasion and metastasis." (PMID 30764547, 2019).
breast carcinoma (continued). "Furthermore, FOXC1 is positively associated with cancer metastasis and poorer prognosis of basal-like breast cancer patients." (PMID 30360388, 2018). "FOXC1 overexpression caused more sensitive to pharmacological inhibition of NF-κB breast cancers." (PMID 29552326, 2018). "In cell culture models of BRCA1-mutant breast cancer, FOXC1 is associated with increased proliferation and may serve as a marker for sensitivity to PARP-inhibitor therapy with olaparib." (PMID 27708239, 2016). "This analysis showed that the patients in this cohort with unmethylated GSTP1 (HR: 7.52, CI: 1.76-32.07, p = 0.006) and FOXC1 (HR: 7.32, CI: 1.11-48.31, p = 0.039) showed a higher risk of dying from breast cancer compared with patients methylated for the same genes." (PMID 20338046, 2010). "Moreover, an association between FOXC1 and chemotherapy resistance has been described in lung cancer, and FOXC1 has been shown to increase chemotherapy resistance and cancer stem cell properties in breast cancer." (PMID 35406487, 2022). "Previous studies have demonstrated that S100A9, FOXC1 and CTGF are involved in the molecular mechanisms underlying organ-specific metastasis in breast cancer." (PMID 40500539, 2025). "It has also been reported that FOXC1 controls the stemness of basal-like breast cancer via Hh signaling, but further work is required to elucidate the signaling sequence." (PMID 41303422, 2025). "For the downstream of the FOXC1 action pathway, the process of promoting breast cancer invasion is more complex, and more transcription factors are involved." (PMID 40003882, 2025). "In breast cancer, PcG proteins promote FOXC1 expression by enhancing H3/H4 acetylation of the FOXC1 promoter." (PMID 40703976, 2025). "Subsequent studies by Alison Hirukawa have further proven that EZH2 sustains the suppression of the FOXC1 gene through H3K27me3, thereby deactivating an anti-invasive transcriptional program driven by FOXC1 in Luminal B breast cancer." (PMID 40003882, 2025). "In breast cancer, abnormally expressed FOXC1 can activate downstream pathways by enhancing NF-KB transcription, thereby facilitating cell growth and metastasis." (PMID 39093497, 2024). "In our study, we analyzed publicly available RNA sequencing data from breast cancer patients, and identified a positive correlation between FOXC1 and L1CAM expression (Pearson correlation coefficient = 0.370, 0.244)." (PMID 38183514, 2024). "In this study, using transcriptomic, epigenetic, proteomic, and bioinformatic analysis, we aim to identify an exhaustive list of FOXC1 targets and cofactors and define, in greater detail, its conserved molecular function across breast cancer." (PMID 39171293, 2024). "Transcription factor (TF) FOXC1 is over-expressed in TNBC and has diagnostic and prognostic value, with its expression correlating with chemoresistance and metastasis in basal-like breast cancer." (PMID 39171293, 2024). "Previous studies have shown that FOXC1 can increase NF‐κB activity in breast cancer cells via enhancing p65 protein stability." (PMID 38107056, 2023). "FOXA1 is a central regulator of gene expression programs in ER+ breast cancer, FOXC1 is associated with EMT and poor prognosis in basal-like breast cancer, and FOXO3 is often dysregulated and plays both tumor-suppressive and oncogenic roles." (PMID 37234983, 2023). "They found that ectopic overexpression of FOXC1 increased breast cancer cell proliferation, migration, and invasion." (PMID 38041134, 2023). "Ray investigated the prognostic value of FOXC1 gene signature in basal-like breast cancer metastasis." (PMID 38041134, 2023). "In a breast cancer model, a reduction in FOXC1 expression retards the development of cancer cells and converts fibroblast-like cells to epithelial cells." (PMID 37626655, 2023).
breast carcinoma (continued). "FOXC1: a therapeutic biomarker specific for basal-like breast cancer, is not only a potential prognostic candidate but also a potential molecular therapeutic target for this subtype of breast cancer." (PMID 37468832, 2023). "FOXC1 is reported to be an oncogene in several cancers like basal-like breast cancer, hepatocellular carcinoma, endometrial cancer, and lymphoma." (PMID 35884426, 2022). "Multiple studies have indicated that FOXC1 upregulation is related to poor prognosis in many cancer types, including acute myeloid leukemia, basal-like breast cancer, liver cancer, pancreatic ductal adenocarcinoma, and gastric cancer." (PMID 35096062, 2022). "Studies have found that the upregulation of FOXC1 is related to the poor prognosis of a variety of human cancers, including acute myeloid leukemia, basal-like breast cancer, hepatocellular carcinoma, pancreatic duct adenocarcinoma, and gastric cancer." (PMID 35096062, 2022). "CXCR4 is a direct transcriptional target of FOXC1 in breast cancer that helps mediate increased invasion and metastasis in a preclinical model." (PMID 34540690, 2021). "For instance, ES in FLNB has been reported to promote EMT in breast cancer by releasing the FOXC1 transcription factor and reducing FLNB nuclear localization." (PMID 34326872, 2021). "Some compelling evidence has pointed that ectopic overexpression of FOXC1 in human basal-like breast cancer cells can contribute to increased tumor cell proliferation." (PMID 34082653, 2021). "Further, FOXC1 overexpression in basal-like MDA-MB-231 breast cancer cells markedly induced phosphorylation of NFκB p65 subunit at Ser-546 and its translocation into the nucleus." (PMID 34540690, 2021). "Previous studies also showed that NF-κB-p65 enhances FOXC1 promoter activity in basal-like breast cancer cells (MDA-MB-468)." (PMID 34094901, 2021). "FGFR1 is a proven transcriptional target of FOXC1 in breast cancer, following its own transcriptional upregulation by TGFβ pathway activation." (PMID 34540690, 2021). "PYR suppresses the proliferation, migration, and invasion of breast cancers through down-regulation of the Akt/p65/FOXC1 pathway." (PMID 34094901, 2021). "Knockdown of FOXC1 expression by siRNA dramatically inhibits proliferation, migration, and invasion of basal-like breast cancer cell lines." (PMID 33968763, 2021). "Transcription factor forkhead box C1 (FOXC1), a known inducer of oncogenesis in breast cancer, has been reported to be overexpressed in basal-like breast cancer (BLBC) to promote CSC traits." (PMID 34572373, 2021). "Despite the well-studied functions and clinical significance of FOXC1 in breast cancer pathogenesis, little is known regarding its regulatory mechanisms." (PMID 33854062, 2021). "The critical function of TF FOXC1 in breast cancer growth and its clinical relevance has been determined." (PMID 33854062, 2021). "Other studies determined that FOXC1 is significantly involved in breast cancer (BRCA) and also colon adenocarcinoma (COAD), pancreatic adenocarcinoma (PAAD), and non–small-cell lung cancer (NSCLC)." (PMID 33981224, 2021). "With regard to a different cytokine, FOXC1 overexpression robustly increased NFκB-driven luciferase activity in breast cancer MDA-MB-231 and MCF-7 cells." (PMID 34540690, 2021). "The data accumulated over the years demonstrate the unique behavior of FOXC1 in cancer, particularly in basal-like breast cancer (BLBC)." (PMID 33981224, 2021). "The second report on FOXC1 expression in Luminal B breast cancer looks at FOXC1 as being predictive of favorable outcome and establishes the use of EZH2 methyltransferase inhibitors as a strategy to block metastasis." (PMID 34540690, 2021). "The clinical evidence with regard to FOXC1 being a powerful prognostic indicator has been most extensively generated in breast cancer." (PMID 34540690, 2021). "Prior studies summarized that FOXC1 is a tumor facilitator in breast cancer, cervical carcinoma, esophageal cancer and melanoma." (PMID 32514244, 2020).